STAT4 (signal transducer and activator of transcription 4)
Diseases named in the same sentence as STAT4 in open-access papers (continued):
Sharing a sentence is not in itself a finding about the gene and the disease.
tumor (120 papers, 2011 to 2025). "STAT4 dysregulation has been previously implicated in immune signaling, inflammation, and tumor aggressiveness, but its role in TNBC remains underexplored." (PMID 41301480, 2025). "IFN-γ activates STAT1 and STAT4, promoting Th1 differentiation, while inhibiting Th2 and Th17 differentiation, with the latter being linked to tumor progression." (PMID 39858472, 2025). "Transcriptomic analysis reveals strong correlations between MET overexpression, PD‐L1 levels, and phosphorylated STAT4, indicating a MET/STAT4/PD‐L1 axis that reprograms tumor‐associated macrophage (TAM) phenotypes." (PMID 40654157, 2025). "In CD8+T cells, the expression levels of RPV2 and STAT4 were elevated with disease progression, suggesting that cell activation was enhanced with the increase of tumor-associated signals." (PMID 38735538, 2024). "Since the protein produced by STAT4 plays an important role in inflammatory processes, mutations in STAT4 can cause an inappropriate signaling pathway process leading to tumor development." (PMID 39337665, 2024). "Defective STAT4‐induced lymphatic metastasis and immune suppression via increased lymph‐angiogenesis with elevated VEGFA expression and decreased production of IFN‐γ with CD4+ cell dependent in STAT4 deficient tumor bearing mice." (PMID 38107057, 2023). "The univariate Cox proportional hazard assay implied clinical features age and tumor size were considered as risk factors of prognosis (hazard ratio > 1, p < 0.05), while the STAT4 score was a protective factor of prognosis." (PMID 38107057, 2023). "The expression of STAT4 was positively associated with PCPG, while STAT4 expression was negatively related to all other tumor types." (PMID 36176415, 2022). "In their models, they showed that STAT4-deficient mice have a significant decrease in their Th1 and Th17 profiles and tumor cytotoxic activity." (PMID 33076315, 2020). "Our results demonstrate that STAT4 deficiency diminishes anti-tumor immune responses and promotes accumulation of immunosuppressive myeloid cell populations to promote HNSCC metastasis." (PMID 32010142, 2019). "In this study, we investigated the effect of host STAT4 deficiency on HNSCC tumor development and metastasis, using an experimental orthotopic model of HNSCC in immunocompetent BALB/c mice and an aggressive, metastatic murine oral cancer cell line, LY2." (PMID 32010142, 2019). "Upstream regulator analysis predicted the increased activation of STAT4, IL-18, and IL-12 pathways in tumor-associated UTCαβ, compared to other T cell subsets." (PMID 31257026, 2019). "One Stat4−/− was removed at day 42, having reached a moribund state associated with advanced tumor progression before terminal sacrifice." (PMID 32010142, 2019). "Our data demonstrates that lymphangiogenesis is upregulated in tumor bearing Stat4 deficient mice, as marked by increased VegfA expression in the lymph node, leading to an immune suppressive microenvironment that favors tumor growth." (PMID 32010142, 2019). "We showed that Stat4−/− mice display a deficient anti-tumor immune response associated with higher rates of metastasis to both the local cervical lymph nodes and the lungs." (PMID 32010142, 2019). "The significantly increased metastasis observed in tumor bearing Stat4−/− mice relative to WT led us to examine the effect of STAT4 deficiency on anti-tumor T cell responses." (PMID 32010142, 2019). "Splenic and lymph node T-cells stimulated with αCD3 antibodies showed a significant reduction of IL-12 production in tumor bearing Stat4 deficient mice." (PMID 32010142, 2019). "Second, except for CD38, NFKB1, and STAT4, the underlying mechanisms of the other five genes in OC progression and the tumor immune microenvironment remained largely unknown and required further investigation." (PMID 41141246, 2025).
tumor (continued). "Mutations in STAT4 can contribute to cancer by modifying immune responses, enhancing inflammation, and altering tumor cell dynamics, which highlights the importance of understanding these mutations in the context of cancer biology and potential therapeutic strategies." (PMID 39337665, 2024). "Also, each G allele of the STAT4 rs7601754 decreases the odds of LSCC with a T2 tumor size by approximately three times under the additive model (OR = 0.332, 95% CI: 0.157–0.706, p = 0.004)." (PMID 39337665, 2024). "Furthermore, increased expression of STAT1 and STAT3 in tumor tissue implicated adverse prognosis whereas higher STAT4 or STAT5 expression meant improved survival." (PMID 36968603, 2023). "Interestingly, primary tumor development and biomarkers associated with HNSCC tumor progression at the tumor site was comparable between WT and Stat4−/− mice." (PMID 32010142, 2019). "Next, to confirm that Stat4−/− T cells from HNSCC tumor bearing mice were deficient in their ability to produce IFN-γ, we re-stimulated splenocytes from tumor bearing WT and Stat4−/− mice with anti-CD3 and anti-CD28 antibodies, then determined IFN-γ production by ELISA." (PMID 32010142, 2019). "Another study linked STAT4 to tumor growth and invasion in colorectal cancer." (PMID 32010142, 2019). "Thus, in the present study, we aim to investigate whether STAT4 influences the anti-tumor immune response and is possibly involved in the initiation or relapse of PAs by examining STAT4 polymorphisms and serum levels." (PMID 39597056, 2024). "Thus, it is possible that the regulation of JAK/STAT signaling in NPC pathogenesis is more complex and diverse than what we previously understood and STAT4 signaling may play a unique role associated with tumor immunity in the tumorigenesis of NPC." (PMID 37393410, 2023). "Our findings indicate that tumor‐intrinsic PD‐1‐mediated MET activation promotes the accumulation of immunosuppressive GITR+ Tregs through IL‐23‐mediated STAT4 phosphorylation in Tregs." (PMID 40673866, 2025). "This study identifies the tumor‐intrinsic PD‐1/MET signaling axis as a key driver of immunosuppressive remodeling in the PDAC microenvironment through the IL‐23/STAT4‐dependent accumulation of GITR+ Tregs." (PMID 40673866, 2025). "STAT4 upregulation, typically linked to Th1 polarization and IFN-γ production, suggests a context-dependent role in enhancing anti-tumor immunity." (PMID 41401147, 2025). "Network analysis highlighted immune-related hub genes (CXCL1, CCL20, IL12B, and STAT4) involved in chemotaxis, leukocyte migration, and cytokine signaling, linking immune dysregulation to tumor development." (PMID 40445003, 2025). "STAT4, a pivotal component of the JAK/STAT4 signaling pathway, contributing to the shaping of the immune microenvironment and regulating transcriptional programs within tumor cells." (PMID 41154358, 2025). "In vivo and in vitro studies over the last few decades have shown that STAT4 can induce inflammation, inhibit tumor growth or promote tumor development by regulating many aspects of the immune response." (PMID 39597056, 2024). "Different types of cytokines can activate STAT4 in different cells, such as tumor or immune cells, via the JAK-STAT pathway." (PMID 39597056, 2024). "By combining the correlation between immune infiltrating cells, GSEA and OS with STAT4, we found a significant correlation between STAT4 and tumor immunity, especially for Tregs that exert immunosuppressive effects." (PMID 38294290, 2024). "Dysregulated STAT4 can lead to chronic inflammation, creating a microenvironment that promotes tumor growth and progression." (PMID 39597056, 2024). "AAV-mediated expression of IL-12 led to STAT4 phosphorylation, interferon-γ (IFNγ) production, infiltration of T cells and, ultimately, tumor regression." (PMID 38558809, 2024).
tumor (continued). "STAT4, a key mediator of inflammation and tumor development, is involved in various signaling pathways, and after phosphorylation, it dimerizes and translocates to the nucleus to act as a transcription factor." (PMID 39911237, 2024). "Conversely, knockdown of STAT4 reduced omental spread and tumor growth in xenograft murine mouse models, and further extended survival following IP injection of HO-8910 OvCa tumor cells." (PMID 37173951, 2023). "All in all, up-regulated expression of STAT4 was revealed to suggest down-regulated LIHC tumor stemness characteristics." (PMID 36968603, 2023). "The impact of the hub gene STAT4 on tumor biological behavior and DNA methylation was experimentally validated or accessed by the TSIDE database." (PMID 37790933, 2023). "Specifically, STAT4 overexpression was correlated with an increased abundance of CAFs within the tumor microenvironment that was further accompanied by increased concentrations of CAF-secreted factors IL6, CXCL12, and VEGFA." (PMID 37173951, 2023). "Using Reactome for pathway enrichment analyses, we observed Trp2Vax and immunotherapy treatment upregulated the IL-12 responsive genes, including ITGB1, SOCS3, IFNG and STAT4 in the tumor-infiltrating CD4+ T cells (with a False Discovery Rate, FDR= 0.0016)." (PMID 36911698, 2023). "The significant and positive correlation (Cor = 0.91, p‐value < 0.001) between T‐cell ratio and STAT4‐positive cell ratio in the 46 primary tumor samples was shown." (PMID 38107057, 2023). "Several studies revealed that STAT4 is not only involved in tumor metastasis, but also promotes EMT and fibroblast proliferation." (PMID 37194066, 2023). "STAT4 functions as a mediator of immunity and tumor growth as an important member of the JAK-STAT pathway." (PMID 37760499, 2023). "Similar to the miR-141/200c cluster, there is conflicting literature on a possible oncogenic or tumor-suppressive role of STAT4 in cancer." (PMID 37173993, 2023). "IHC results demonstrated that the expression levels of CDH4, CYLD, and STAT4 were stronger in adjacent basal epithelium compared to that in tumor cells (p < 0.001)." (PMID 37393410, 2023). "Here, we demonstrate data that for the first time implicate an anti-proliferative and potentially tumor-suppressive role of STAT4 in T-PLL." (PMID 37173993, 2023). "Based on TCGA ccRCC dataset, tumor tissues had much higher STAT4 mRNA levels than normal, which was further confirmed by the data from the 21 paired resected samples." (PMID 36348434, 2022). "Another STAT, STAT4, has also emerged as a tumorigenic gene that triggers tumour metastasis and progression." (PMID 35224833, 2022). "In the greatest number of tumors, STAT4 was correlated with tumor growth, then STAT1, STAT3, STAT6, STAT5B, STAT2, and STAT5A." (PMID 36176415, 2022). "STAT4 has been influential in other tumor entities, but remains nearly unresearched in PCa, requiring further investigations." (PMID 34638338, 2021). "The forest plots of the IL12 signaling mediated by STAT4 show that the pathway is differentially coexpressed between tumor and normal in 9 out of the 11 cancer types (p-statistics<0.05)." (PMID 33945541, 2021). "In vivo studies regarding HNSCC showed a higher rate of metastasis in STAT4−/−- mice indicating a role of STAT4 in preventing tumor metastasis in HNSCC." (PMID 34638338, 2021). "The main anti-tumor actions of IL-12 are promoted by a specific signaling pathway that includes STAT4 and interferon gamma (IFNG)." (PMID 32973967, 2020). "Distinct types of cytokines can activate STAT4 in multiple cells such as tumor or immune cells via the JAK-STAT pathway." (PMID 32226303, 2020). "Our results show a novel mechanism by which entinostat initiates an IFIT1-STING-mediated potentiation of STAT4 via IRF1 to augment NK cell-mediated anti-tumor responses." (PMID 32499867, 2020).
tumor (continued). "In OE relative to DIE, natural-killer-cell-mediated cytotoxicity is directed against tumor-cell target, cell-cycle arrest, and cell migration, and tyrosine phosphorylation of Stat4 protein." (PMID 32429215, 2020). "Necropsies performed at terminal sacrifice revealed that Stat4−/− mice displayed comparable primary tumor growth to the WT mice." (PMID 32010142, 2019). "Each of these myeloid cell populations are known to inhibit the ability of T lymphocytes to expand and exert their cytotoxic functions, suggesting a potential mechanism behind the impaired T cell anti-tumor responses observed in tumor bearing Stat4−/− mice." (PMID 32010142, 2019). "We chose to focus on metastatic immunological sites and systemic immune responses, given that primary tumor development was similar between tumor bearing WT and Stat4−/− mice." (PMID 32010142, 2019). "Immunofluorescence staining of tumors of WT and Stat4−/− mice confirmed T cell infiltration to oral tumor sites." (PMID 32010142, 2019). "Taken together, our data demonstrates increased metastatic progression in tumor bearing Stat4−/− mice compared to tumor bearing WT mice." (PMID 32010142, 2019). "This is further supported by the significant attenuation of IL-17 production by T cell re-stimulated splenocytes and the diminished expression of Rorgc (a TH17 transcription factor) in the spleens of tumor bearing Stat4−/− mice." (PMID 32010142, 2019). "Future studies will determine the exact role these cells play in tumor progression and metastasis, and the involvement of STAT4 in this process during HNSCC." (PMID 32010142, 2019). "Up to this point, the functions of STAT4 in carcinogenesis and tumor metastasis are paradoxical, appearing to be dependent on the cancer type." (PMID 32010142, 2019). "While STAT2 and STAT4 promote the anti-tumor immune response, STAT3 and STAT6 mediate immunosuppression in the TME, and STAT1 and STAT5 have been implicated in both activation and suppression of the anti-tumor immune response." (PMID 31057536, 2019). "Taken together, the significantly increased expansion of immunosuppressive myeloid populations in Stat4−/− mice potentially promotes tumor metastasis in HNSCC." (PMID 32010142, 2019). "The primary difference between tumor bearing WT and Stat4−/− mice lied in the inability of Stat4−/− mice to prevent the establishment of tumors at metastatic sites (lymph nodes and lungs)." (PMID 32010142, 2019). "We therefore analyzed IL-17 production in draining lymph nodes and spleens of tumor bearing WT and Stat4−/− mice." (PMID 32010142, 2019). "Further, Klrc1, an NK cell marker, were decreased in the draining lymph nodes and spleens of Stat4−/− mice with lung metastases, indicating diminished anti-tumor response by cytotoxic lymphocytes." (PMID 32010142, 2019). "Flow cytometric analysis of F4/80 expression as measured through mean fluorescence intensity revealed that granulocytic CD11b+Ly6CintLy6Ghi cells in the spleens and bone marrow of tumor bearing Stat4−/− mice over-expressed this cell surface receptor." (PMID 32010142, 2019). "The observed increase in tumor-promoting myeloid populations in the spleens and lymph nodes of Stat4−/− mice led us to determine their immunosuppressive potential." (PMID 32010142, 2019). "F4/80 expression among CD11b+Ly6Chi Ly6G− cells was similar between tumor bearing WT and Stat4−/− mice." (PMID 32010142, 2019). "This was not surprising given the similar tumor volumes observed at the primary site of tumor bearing WT and Stat4−/− mice, in contrast to the increased lymph node metastatic sites seen in Stat4−/− mice." (PMID 32010142, 2019). "Taken together, our data demonstrates a significant accumulation of MDSC populations in metastatic Stat4−/− mice which potentially contributes to an immunosuppressive tumor microenvironment and subsequent metastasis in HNSCC." (PMID 32010142, 2019).
tumor (continued). "Tumor bearing Stat4−/− mice showed trends toward decreases in CD4+ and CD8+ cells in lymph nodes and spleens, which was more pronounced in metastatic cases." (PMID 32010142, 2019). "TIM3, a potent T cell suppressor of the immune response, was found to be significantly overexpressed in the lymph node and splenic CD4+ and splenic CD8+ T cells of metastatic Stat4−/− mice compared to tumor bearing WT mice." (PMID 32010142, 2019). "Histological analysis of the lungs and lymph nodes by a certified pathologist confirmed that metastasis to these sites occurred at a much higher rate in tumor bearing Stat4−/− mice compared to tumor bearing WT mice." (PMID 32010142, 2019). "Further, we observed a significant decrease in TH1, TH17, and cytotoxic activity in tumor bearing Stat4−/− compared to WT mice." (PMID 32010142, 2019). "Our flow cytometry results correlated with gene expression of the TH17 transcription factor Rorgc in the spleens and lymph nodes, while tumor Rorgc expression were similar in WT and Stat4−/− mice." (PMID 32010142, 2019). "Even more significant than a reduction in CD4+ and CD8+ T cell numbers in Stat4−/− tumor bearing mice, was the strikingly elevated expression of the immunosuppressive markers PD-1 and TIM3 on splenic CD4+ and CD8+ T cells." (PMID 32010142, 2019). "Our results showed that SSa upregulated the gene expression of IL-12, IL-12R, and STAT4 and increased protein amounts and in situ expressions of IL-12, IL-12R, and pSTAT4 in tumor tissues." (PMID 31214035, 2019). "TNF-α+ production by T cells in draining lymph nodes were comparable between WT and Stat4−/− tumor bearing mice, while splenic T cell TNF-α production was slightly attenuated in Stat4−/−tumor bearing mice." (PMID 32010142, 2019). "Spleens and draining lymph nodes of tumor bearing Stat4−/− mice were found to contain increased accumulation of CD11b+Ly6G+Ly6Cint and CD11b+Ly6G−Ly6Chi cells compared to WT controls, particularly in metastatic mice." (PMID 32010142, 2019). "In B-ALL patients, 173 candidates were identified to be significantly associated with GATA3 expression, including some reported GATA3-related genes (e.g., ITM2A) and well-known tumor-related genes (e.g., STAT4)." (PMID 28415601, 2017). "Functional experiments showed that overexpression of the JCHAIN inhibited tumour migration and invasion, which may be closely related to the activation of the IL-2/STAT4 signalling pathway." (PMID 41010015, 2025). "Reduced STAT4 expression may, therefore, impair the activation of pro-inflammatory pathways, favoring a tumor microenvironment conducive to disease progression." (PMID 40733498, 2025). "STAT4 can also alter the tumor microenvironment by influencing the growth factors and cytokines levels, which may indirectly affect tumor cell growth and apoptosis." (PMID 39337665, 2024). "Since it can be activated in both tumor and immune cells, it is suspected that STAT4 may modulate the interaction between tumor cells and host immunity." (PMID 39597056, 2024). "STAT4 has been shown to play a role in tumor progression in CRC." (PMID 39408697, 2024). "These genes, which are involved in tumor immunity and are unfavorable to patient survival, may be downstream genes of STAT4 affecting patient prognosis." (PMID 38294290, 2024). "For monitoring tumor malignancy, STAT4 alone or (STAT4 + LMP1) could acquire an equally higher accuracy rate (70.59%)." (PMID 37393410, 2023). "In comparison to STAT1, STAT4 expression was lower in all tumor progression stages and on a downward trend, which could be used to monitor tumor progression and formulate therapeutic options in clinical tumor therapy." (PMID 36968603, 2023). "Importantly, the elevated and specific expression of STAT4 was observed in T cells, and further minor annotations implied that STAT4 was expressed in multiple anti‐tumor T‐cell subtype: CD4+ T cells, CD8+ T cells, NK T cells, NK cells, and cycling T cells." (PMID 38107057, 2023).